LGALS1 (galectin 1)
Diseases named in the same sentence as LGALS1 in open-access papers (continued):
Sharing a sentence is not in itself a finding about the gene and the disease.
tumor (continued). "Further multivariate analyses demonstrated that factors of primary tumor status (T1, relative risk (R.R.)= 2.732; T2–T4, R. R. = 9.346), mitotic rate (R.R. = 2.048), and galectin-1 level (R.R. = 4.628) independently predicted MFS, respectively." (PMID 29671787, 2018). "Galectin-1 has been extensively studied and is implicated in tumour transformation, cell cycle regulation, apoptosis, cell adhesion, migration and inflammation by modulating cell-cell and cell-matrix interactions." (PMID 28841682, 2017). "Galectin-1 is an overexpressed mammalian lectin that is associated with tumour-invasive characteristics and cell adhesion and polarization, as well as in vivo tumour growth and EMT91–93." (PMID 28701735, 2017). "As one mechanism by which tumor cells develop drug resistance is associated with resistance to apoptosis, it seems paradoxical that galectin-1 on one hand induces apoptosis, and on the other hand contributes to drug resistance." (PMID 27050374, 2016). "Gal-1, encoded by LGALS1, is a secreted protein that is overexpressed in both the stroma surrounding tumor cells and cancer-associated endothelial cells." (PMID 27835885, 2016). "The overexpressed galectin-1 is localized both in the stroma surrounding the tumor cells and in the cancer associated endothelial cells." (PMID 27223428, 2016). "The poor prognosis associated with elevated galectin-1 expression is related to tumor evasion of the immune response." (PMID 27649167, 2016). "There is compelling evidence for galectin-1 as an important protein in cancer biology that is enriched in the tumor- associated neovascular endothelium." (PMID 27223428, 2016). "Stable galectin-1 knockdown was achieved via transduction of parental GL261 tumor cells with a lentiviral vector encoding a galectin-1-targeting miRNA." (PMID 26137448, 2015). "Both galectin-1 and galectin-3 interact with oncogenic Ras, a proto-oncogene known to be mutated and constantly expressed in tumor cells rendering these two galectins to be favorable targets for therapy." (PMID 25730388, 2015). "Galectin-1 has been associated with a variety of physiological cell functions; it was shown to be important for tumor development and metastasis and has been associated with cell adhesion, invasion, angiogenesis and the immune response." (PMID 26413750, 2015). "Our report demonstrates that high galectin-1 expression in cancer-associated stroma correlates with various clinic pathologic parameters, such as tumor invasiveness, advanced stage, metastasis and higher recurrent rate." (PMID 26589590, 2015). "Increased expression of galectin-1 and/or galectin-3 has been reported to be associated with tumour progression." (PMID 23799140, 2013). "We and others have observed an overexpression of either galectin-1 or galectin-3 in tumour-associated ECs." (PMID 23799140, 2013). "Accordingly, the upregulation of galectin-1 in tumor-associated endothelial cells is postulated as a tumor escape mechanism from immune response." (PMID 19055814, 2008). "The activation of endothelial cells, e.g. with lipopolysaccharides, or tumor-conditioned media results in a rapid increase of galectin-1 expression, and it is constitutively expressed in tumor-associated endothelial cells." (PMID 19055814, 2008). "Galectin-1, a member of this family, contributes to different events associated with cancer biology, including tumour transformation, cell cycle regulation, apoptosis, cell adhesion, migration and inflammation." (PMID 15785741, 2005). "Within the immune system, galectin-1 influences the activation of dendritic cells, natural killer cells, B-cells, and T-cells and their downstream effects, as well as influences myeloid-derived suppressor cells and tumor-associated macrophages." (PMID 41918780, 2025). "In addition, specific protein abundance of the immunomodulatory proteins TIMP1 and Galectin-1 were lower in VHL-restored tumors compared to VHL-mutated tumor spheroids." (PMID 40736709, 2025).
tumor (continued). "Furthermore, we and others found that endothelial cells can also exploit extrinsic galectin-1 that is secreted by tumor cells or cancer associated fibroblasts to increase their angiogenic potential." (PMID 38990363, 2024). "Interestingly, combination therapy reshaped the tumor microenvironment via cytokines associated with natural killer cells, supported by eradication of immune checkpoint galectin-1 and elevated granzyme B levels." (PMID 38160212, 2024). "LGALS1 expression in tumor cells has been linked to immunosuppression, but its induction in microglia might be relevant for inflammatory responses." (PMID 38499808, 2024). "High levels of galectin-1 were found in the vascular endothelium of primary tumors in the lung, colon, head and neck, and oral cancers, and this high expression was usually associated with tumor-induced hypoxia, and angiogenesis." (PMID 36873388, 2023). "This study analyzes galectin-1, -3, and -9 serum concentrations in breast cancer patients through enzyme-linked immunosorbent assay (ELISA) against the characteristics of the patient and the tumor such as stage, molecular subtype, and receptor expression." (PMID 37568625, 2023). "Galectin-1 enhances fibrosis of PDAC tumor stroma through interaction with tumor-associated cells." (PMID 36428567, 2022). "Furthermore, pathogenic bacteria can also block antitumor immunity by recruiting myeloid-derived suppressor cells into the tumor environment and upregulating galectin-1 expression in tumor-associated γδ T cells." (PMID 35633703, 2022). "Of note, when galectin-1 was included in a panel with three other autoantibodies, the diagnostic value was comparable to a combination of the classical tumor markers CEA (carcinoembryonic antigen) and SCC-Ag (squamous cell carcinoma antigen), i.e., 32% and 40% sensitivity, respectively." (PMID 36497271, 2022). "Vimentin gene expression was found to be strongly positively correlated with focal adhesion and extracellular matrix (ECM) turnover, hallmark processes in the tumor microenvironment during tumor angiogenesis, as well as with other described tumor endothelial markers, e.g., galectin-1 8,11,16." (PMID 35606362, 2022). "As key regulators of tumor immune evasion, high LGALS1 expression in AML patients was associated with higher macrophages M2, monocytes infiltration, and lower naive T cells CD4, naive B cells, and resting mast cells infiltration, which remained consistent with a previous study." (PMID 35127715, 2021). "Moreover, Galectin-1 overexpression in PSCs was strongly associated with increased expression of EMT markers in both the orthotopic xenograft tumor in the pancreas and in metastatic lesions of naked mice." (PMID 29156810, 2017). "In accordance with the results from studies on other cancer associated malignancies, we also found, galectin-1 to be consistently overexpressed in the tumor-associated stroma of TNBC patients with significantly lower expression in benign breast and normal tissues from other organs." (PMID 27223428, 2016). "Further analysis of tumor cell-associated galectin-1 expression in ERBB2 tumors is therefore required to determine whether this is associated with poor prognosis." (PMID 26883193, 2016). "Indeed, increased galectin-1 expression is generally associated with poor prognosis in different tumor types." (PMID 26066796, 2015). "Our results suggest that galectin-1 might play a role in tumor progression and be associated with poor outcome in EOC." (PMID 26589590, 2015). "Increased levels of galectin-1 have been linked to tumor cell migration and invasion." (PMID 26413750, 2015). "This suggests that galectin-1 expression is associated with more aggressive tumor growth." (PMID 26066796, 2015). "In addition, the increased expression of galectin-1 and/or galectin-3 has been reported to be associated with tumour progression." (PMID 23799140, 2013).
tumor (continued). "Indeed, abrogating galectin-1 expression renders tumor cells more susceptible to temozolamide treatment." (PMID 22583806, 2012). "Over-expression of the galectin-1 protein in the liver of Mdr2-KO/HCV-Tg mice may also cause inhibition of anti-tumor immune response." (PMID 19340302, 2009). "Whether expression of galectin-1 in tumour tissue or tumor-associated stroma may actively influence disease outcome still remains to be elucidated." (PMID 15785741, 2005). "Interestingly, overexpression of galectin-1 in tumour cells results in an increase in both the membrane association of H-RAS and cell transformation." (PMID 15785741, 2005). "Finally, the strong expression of mRNA encoding galectin-1 and 3 in malignant T cells suggests the secretion of these proteins; both have been shown to suppress anti-tumor responses, favor Th2 inflammation and polarize the epidermal environment to a pro-tumorigenic state." (PMID 39169943, 2024). "Furthermore, tumor galectin-1 is closely associated with hypoxia." (PMID 37047471, 2023). "Moreover, a higher expression level of galectin-1 was associated with increased local tumor relapse and poor cancer-specific survival in patients with stage I-II cervical tumors after radiation treatment, although it could not predict distant metastasis." (PMID 30208169, 2018). "Overall, these findings delineate a tumor-intrinsic signaling axis in which PD-L1 upregulates Livin and Galectin-1 to sustain PI3K/AKT activity and drive SKP2-dependent cell proliferation." (PMID 41898602, 2026). "Galectin-1 (Gal-1/LGALS1), a β-galactoside-binding lectin frequently overexpressed in OSCC, is associated with tumor progression and unfavorable prognosis; however, its involvement in ferroptosis regulation remains incompletely understood." (PMID 41827716, 2026). "In contrast, exosomes derived from Galectin-1 gene knockout tumor cells were unable to induce T cell suppression." (PMID 41484095, 2026). "Silencing galectin-1 suppressed proliferation, motility, side population fraction, and tumorsphere formation in vitro, and impaired tumor initiation and growth in vivo, whereas overexpression enhanced these malignant phenotypes." (PMID 42157933, 2026). "Among them, Galectin-1, Galectin-3, and Galectin-9 have been most extensively investigated for their multifaceted roles in shaping the tumor microenvironment." (PMID 42129932, 2026). "Proteomic profiling of MSC-exosomes identified key proteins, including ANXA1, ANXA2, EEF2, LGALS1, and PKM2, associated with tumor regeneration and chemotherapy response." (PMID 41683993, 2026). "Human galectin-1 (hGal-1) is an abundant β-galactoside-binding animal lectin that plays an essential role in promoting the immunosuppressive tumor microenvironment." (PMID 41643145, 2026). "Galectin-1 (LGALS1) has roles in tumour angiogenesis and immune regulation but also enhances osteoblast differentiation of MSCs." (PMID 41677278, 2026). "LGALS1 expression in tumor cells promotes the polarization of macrophages toward an immunosuppressive M2 phenotype, facilitating tumor growth." (PMID 40710421, 2025). "In tumour stroma, galectin-1 is an essential player in the induction of myCAFs from resident fibroblasts; this effect seems to be TGFβ-independent." (PMID 41009413, 2025). "Key genes such as LGALS1, PLA2G5, and FABP5 were upregulated in high-risk patients and enriched in M2-like tumor-associated macrophages." (PMID 41164132, 2025). "To investigate the impact of LGALS1 on tumor progression, we first compared the expression levels of LGALS1 between lymph nodes and primary tumors with positive or negative lymph node metastasis using immunohistochemistry." (PMID 40881692, 2025). "A key role of Galectin-1 in tumor development is converting the tumor microenvironment into an immune "cold" state, thus fostering an immunosuppressive environment that promotes tumor formation and growth." (PMID 40134029, 2025).
tumor (continued). "The expression of Vimentin, Snail, and Slug was significantly reduced in the tumor tissues obtained through xenografts using miR-22-3p stable cells and galectin-1 knockdown cells." (PMID 39996781, 2025). "By contrast, Galectin-1 is synthesized mainly inside tumor cells in hepatocellular, colorectal, and breast carcinomas, where it supports proliferation, angiogenesis, and metastatic spread." (PMID 40710343, 2025). "During tumor evolution, fatty acid metabolism was upregulated, and active fatty acid metabolism involving LGALS1 was related to HNSCC cell metastasis." (PMID 40881692, 2025). "The hypoxic tumor microenvironment further elevates Galectin-1 expression, exacerbating the immunosuppressive milieu within tumors." (PMID 40134029, 2025). "For example, lowering the expression of galectin-1 suppresses vascularization in prostate cancer, while upregulated galectin-3 stimulates cell proliferation and invasion of tumor cells." (PMID 40649198, 2025). "Recent advances in experimental and clinical research have shed light on the complex roles of galectin family members—particularly Galectin-1, -3, and -9—in shaping the tumor microenvironment and driving disease progression." (PMID 40710343, 2025). "As with the miR-22-3p results, tumor growth in the galectin-1 knockdown group was also significantly decreased compared with that in the control group (p < 0.05)." (PMID 39996781, 2025). "Elevated expression for transcripts IGFBP2 and LGALS1 in cells at the tumor periphery (GBM-LE region) indicate aberrant ECM remodeling at the invasive GBM edge." (PMID 41366031, 2025). "Among the various roles of galectin-1 in cancer, cell proliferation has been reported to act differently depending on cancer cell type, tumor immune privilege, and galectin-1 interactions with specific cell-surface glycoproteins or intracellular proteins." (PMID 39996781, 2025). "miR-22-3p negatively regulates galectin-1 expression and the two molecules have opposite patterns of oncogenic and tumor-suppressive functions, respectively; furthermore, these two molecules are associated with metastasis-free survival." (PMID 39996781, 2025). "Galectin-1 is involved in tumor invasion, metastasis, and EMT as it controls the expression of MMP-2, MMP-9, and TIMP." (PMID 39996781, 2025). "Consistently, Western blot analysis confirmed markedly up-regulated protein expression of ALOX5AP and LGALS1 in GBM tumors versus non-tumor tissues." (PMID 41164132, 2025). "In this study, we review the roles that galectin-1 (Gal1) plays in suppressing immune surveillance in the tumour microenvironment." (PMID 40507367, 2025). "Galectin-1 is a potential target for treatment to prevent tumor metastases, as it has a role in the transmission of tumors from primary locations to widespread metastases." (PMID 41480246, 2025). "Tumor galectin-1 (Gal-1) levels were inversely related to immune checkpoint inhibitor (ICI) treatment in HNSCC patients." (PMID 41511327, 2025). "LGALS1 expression was enriched in the M2-like macrophage clusters (an immunosuppressive phenotype), consistent with its putative role in promoting tumor progression." (PMID 41164132, 2025). "Compared with mock transfection, the number of lung metastases in nude mice with LGALS1 knockdown was significantly reduced, suggesting that LGALS1 can significantly promote tumor metastasis in vivo." (PMID 40881692, 2025). "Therapeutic strategies have been developed to target the role of Galectin-1, including small-molecule and mAb Gal-1 inhibitors and positron emission tomography imaging for noninvasive profiling of tumor microenvironment." (PMID 41918780, 2025). "Studies have shown that LGALS1 is significantly overexpressed in the tumor microenvironment of DLBCL, and its high expression is closely related to resistance to CD20 monoclonal antibody therapy." (PMID 41189944, 2025).
tumor (continued). "This review focuses on galectin-1 (Gal1), a protein that helps tumours evade the immune system by weakening T cell responses, altering cytokine production, and promoting tumour-supporting immune cells and blood vessels." (PMID 40507367, 2025). "Galectins have emerged as key modulators of tumour–immune interactions, with Galectin-1 (Gal1) being the most well-studied member." (PMID 40507367, 2025). "Galectin-1 is now recognized as a multilayered orchestrator of tumor progression, acting through both cellular signaling and matrix-modifying routes." (PMID 40710343, 2025). "For example, we reported on elevated galectin-1 expression in tumor endothelium vs. normal endothelium in colon carcinoma, breast carcinoma and sarcoma." (PMID 38990363, 2024). "We found a potential mechanism that AML cells can inhibit CAR T cells’ anti-tumor function, and this effect is galectin-1-dependent blockade of surface CAR expression." (PMID 38184596, 2024). "For instance, studies performed in mouse tumor models, including our own work on ovarian cancer, identified IL-17- or galectin-1-producing γδ T cells as tumor-promoting, immunosuppressive cell types." (PMID 38541651, 2024). "The discovery of the role of galectin-1 in cell surface CAR down-regulation provides important insights for developing strategies to restore anti-tumor functions." (PMID 38184596, 2024). "The researchers emphasized the clinical importance of serum galectin-1 as a non-invasive biomarker for the early detection of OC, for the monitoring of response to treatment, and as an indicator of tumor metastasis and invasion." (PMID 38732363, 2024). "Others found increased galectin-1 expression in tumor endothelium from oral squamous cell carcinoma, prostate cancer, lung cancer and head and neck cancer." (PMID 38990363, 2024). "The gene LGALS1 was found as the most commonly upregulated transcript in cancer cells of different tumor types." (PMID 38384845, 2024). "Tumor-secreted Galectin-1 can bind to glycosylated receptors on immune cells and trigger the suppression of immune cell function in the tumor microenvironment, contributing to the immune evasion of tumors." (PMID 39840036, 2024). "One trial has demonstrated that galectin-1 attenuated tumor response to radiation, and that, by inhibiting galectin-1 in addition to radiation treatment, there was a decreased tumor growth and dissemination." (PMID 38539500, 2024). "The role of endothelial galectin-3 in tumor immunomodulation is still not fully understood but it appears that this family member acts somewhat more ambiguous as compared to galectin-1." (PMID 38990363, 2024). "Anginex is a peptide-based galectin-1 inhibitor that has demonstrated the potential to inhibit tumor growth, proliferation, and angiogenesis." (PMID 38927753, 2024). "Beyond direct immune cell killing, galectin-1 can prevent further T cell infiltration into the tumor via upregulation of galectin-9 and PDL1." (PMID 38254801, 2024). "For example, we recently published that vaccination against galectin-1 can increase tumor infiltration of cytotoxic CD8 + T cells resulting in reduced tumor growth." (PMID 38990363, 2024). "HRS cells overexpress key immunosuppressive molecules like IL-10, TGF-beta, and galectin-1 to create an immune-suppressive microenvironment and prevent effective anti-tumor immune responses." (PMID 38539461, 2024). "It was also found that TREM2-positive TAMs produced a greater amount of galectin-1, which influences PD-L1 overexpression in tumor vessels, and attenuates CD8+ T cell infiltration." (PMID 39408564, 2024). "LGALS1 has been found to be involved in regulating immunosuppressive microenvironments to regulate tumor progression in many human cancers." (PMID 38205232, 2024). "Tumor secreted Galectin-1 has immunosuppressive effects and serves as an important marker in diagnosis, prognosis, and treatment of cancer." (PMID 38881904, 2024).